ENSG00000287323 (novel transcript)
Gene: Long non-coding RNA gene on chromosome 5 (149,694,212 to 149,696,477, forward strand). Ensembl gene ENSG00000287323.
Gene Ontology:
Biological process: RNA processing
Cellular component: nucleolus